CD4 (CD4 molecule)
Diseases named in the same sentence as CD4 in open-access papers (continued):
Sharing a sentence is not in itself a finding about the gene and the disease.
Hepatic steatosis (29 papers, 2008 to 2025). Steatosis is a term used to denote lipid accumulation within hepatocytes. "This suggests that in South African PHIV children longer duration of HIV suppression and higher CD4 count may be protective against hepatic steatosis, although being overweight and obese remain risk factors for hepatic steatosis." (PMID 35757117, 2022). "A study showed that exosomes transferring miR-107 targeted the regulation of Foxp1 in clusters of differentiation 4 positive T (CD4+T) cells for the development of fatty liver disease." (PMID 37600712, 2023). "Our study identified human CD4+ T cells as a key player in promoting liver steatosis-fibrosis progression." (PMID 33013934, 2020). "Patients with hepatic steatosis have increased intrahepatic IL-17 expressing CD4+ T cells while in the blood, more IFNy secreting CD4+ T cells are detected as compared to healthy controls." (PMID 30619297, 2018). "The results show that the supplemented animals had a higher frequency of Foxp3+ CD4+ (Treg) cells in mesenteric lymph nodes, less hepatic steatosis, higher levels of MDA, lower levels of vitamin E, and differences in the size of muscle fibers compared to non-supplemented IL−10−/− mice." (PMID 38474762, 2024). "Longer suppression of HIV viraemia and higher CD4 count were associated with lower CAP and might be protective factors for hepatic steatosis in PHIV children." (PMID 35757117, 2022). "Furthermore, both hepatic steatosis and the infiltration of inflammatory cells were attenuated in mice that received Il17+/+ CD4+ T cells, as determined by histological analysis, and the levels of ALT and AST also decreased." (PMID 35266816, 2022). "Thus, T cell-specific Atg7 deficiency not only diminished the CD4+ and CD8+ T cell populations but also severely reduced the percentage of hepatic NKT cells, which may have contributed to impaired hepatic steatosis development as suggested by literature." (PMID 30619297, 2018). "Since hepatic steatosis was decreased upon T cell-specific deletion of Atg7, we hypothesized that this was due to a reduction in the numbers and profile of cytokine secretion of CD4+ and CD8+ T cells in the livers of Lck-Cre Atg7f/f mice." (PMID 30619297, 2018). "Additionally, the increase in CPT1 expression may also produce an immunosuppressive microenvironment through increasing CD4+ T cell apoptosis in the setting of fatty liver disease as we have shown." (PMID 29795111, 2018). "Homeostatic cholesterol biosynthesis is necessary for immune resolution by CD4+ cells in a c-MAF-AP-1-dependent manner, which drives IL-10 production that was shown to be protective against diet-induced fatty liver disease in mice." (PMID 40510344, 2025). "In the condition of HFD-induced NAFLD, we also found that Prf−/− mice developed more severe hepatic steatosis with more macrophage and IFN-γ, producing CD4+ T cell infiltration of the liver." (PMID 32528465, 2020). "In liver steatosis, PD1 and 2B4 expression were higher in the CD8 T cell population than the CD4 T cell population." (PMID 30949049, 2019). "In conclusion, although Atg7 deficiency resulted in a relative increase in T cells which produce inflammatory cytokines, the decrease in CD4+ and CD8+ T cells in the liver likely impairs the development of hepatic steatosis in Lck-Cre Atg7f/f mice." (PMID 30619297, 2018). "In further phenotypic studies, hepatic steatosis was not different between FFC-fed CD4−/− and WT mice, as evident from H&E staining and biochemical quantification of liver triglycerides." (PMID 40631180, 2025). "Accordingly, we observed elevated IL-17A–expressing CD4+ T cells in the livers of obese mice lacking LKB1 in DCs, a feature that was associated with enhanced hepatic steatosis." (PMID 37140993, 2023). "Thus, in liver steatosis, CD8 T cell response is functionally suppressed by overexpression of inhibitory T cell receptors PD1 and 2B4 whereas CD4 T cell response is limited by decreased cell numbers." (PMID 30949049, 2019).
Hepatic steatosis (continued). "FMT effectively decreased CD3+CD4+ T cells, CD3+CD8+ T cells and M1 macrophages in liver and Th1 cells in MLN, whereas it increased Treg cells, thereby decreasing plasma ALT, AST, TG and TCHO, as well as histologically attenuating hepatic steatosis and lipid accumulations, thus improving NAFLD." (PMID 37095192, 2023). "No change with significant differences: hepatic steatosis and fibrosis levels as measured by transient elastography, LiverFAST analysis (steatosis, fibrosis and inflammation scores), ALT, TC, TG, fasting glucose, CD4+ T lymphocytes, CD8+ T lymphocytes and ZO-1." (PMID 37457967, 2023).
Hypercholesterolemia (29 papers, 2008 to 2026). An increased concentration of cholesterol in the blood. "Elevated CD4+T cell counts were linked to higher lipid levels, and naive CD4+T cells showed a positive association with peripheral blood hypercholesterolemia." (PMID 38666515, 2024). "Recently, a cholesterol-rich diet or hypercholesterolemia in mice was associated with an increased number of splenic CD4 T-cells." (PMID 22723880, 2012). "Importantly, diet-induced hypercholesterolemia in B6 mice was also associated with decreased sensitivity to ATP in CD4+ and CD8+ T cells, highlighting the relationship between cholesterol intake and the amplitudes of P2X7-induced cellular responses in T cells." (PMID 35743168, 2022). "Furthermore, we also observed that hypercholesterolemia was associated with a higher CD4 cell count, a lower HIV-1 plasma viral load, the presence of clinical signs of lipodystrophy and older age." (PMID 18923695, 2008). "Western diet-induced hypercholesterolemia in mice was found to promote CD4+T cell differentiation in the liver." (PMID 32645995, 2020). "Here we report that hypercholesterolemia promotes TCR stimulation in CD4+ T cells and facilitates proliferative T cell responses." (PMID 29142309, 2017). "In this study, we demonstrate that hypercholesterolemia increased the homeostatic TCR signaling in CD4+ T cells." (PMID 29142309, 2017). "Recently it was reported that hypercholesterolemia progressively decreased CD4+ regulatory T cells in the aorta as the mice aged and cholesterol diet continued." (PMID 24647529, 2014). "Dietary lowering of hypercholesterolemia prevented such a decrease of CD4+ regulatory T cells in the aorta." (PMID 24647529, 2014). "However, levels of IL-2 and IL-6 were negatively correlated with activated CD4+ T cells in patients with hypercholesterolemia." (PMID 29997625, 2018). "However, Il-2 and IL-6 were negatively correlated with activated CD4+ T cells in patients presenting with hypercholesterolemia." (PMID 29997625, 2018). "In other research, circulating hypercholesterolemia in humanized mice, induced by adeno-associated virus 8–PCSK9 treatment and Western diet, resulted in disrupted human T cell homeostasis with enhanced blood, and hepatic and lung CD4+ and CD8+ memory T cells, while Treg cells were decreased." (PMID 32645995, 2020). "Thus, our findings may help to understand why hypercholesterolemia correlates with altered CD4+ T cell responses." (PMID 29142309, 2017). "The multivariate linear regression analysis showed that gender, CD4+ T cell count and/or WHO clinical stage categories, being anemic or normal, being hypercholesterolemia or normal were found to be independent predictors of HIV RNA load (p < 0.05)." (PMID 30064395, 2018). "Therefore, our model was suitable for evaluating the link between P2X7 sensitivity in CD4+ and CD8+ T-cell subsets and increasing cholesterol levels in the plasma membrane due to diet-induced hypercholesterolemia." (PMID 35743168, 2022). "Moreover, we assessed the outcome of a high-fat/cholesterol (HFC) diet-induced hypercholesterolemia on the plasma membrane cholesterol content and the functionality of P2X7 in CD4+ and CD8+ T cells." (PMID 35743168, 2022). "We therefore evaluated whether diet-induced hypercholesterolemia in B6 mice can modulate the amplitude of P2X7-mediated pore formation and CD62L shedding in CD4+ and CD8+ T cells at different stages of differentiation." (PMID 35743168, 2022). "Hypercholesterolemia mediates CD4+ T cell inflammatory response, but it is not completely clear how CD4+ T cell together with cholesterol induces long-term inflammatory diseases." (PMID 33505215, 2021).
Hypercholesterolemia (continued). "On the other hand effector CD4+ T cells progressively increased while on cholesterol diet but reversal of hypercholesterolemia did not reduce these cells in aortic lesions." (PMID 24647529, 2014). "An unexpected finding in the present study was that the initial pro-inflammatory response to hypercholesterolemia was started by CD8+ T cells and not by CD4+ T cells." (PMID 21126329, 2010).
hyperlipidemia (29 papers, 2005 to 2025). "Additionally, the risk of hyperlipidemia in patients with baseline CD4+ T-cell count >500 cells/μL was 2.69 times higher than that in patients with baseline CD4+ T-cell counts <200 cells/μL." (PMID 35929632, 2022). "In conclusion, in antiretroviral-experienced patients with HIV-1 RNA <50 copies/mL and CD4+ counts >500 cells/mm3, substituting abacavir for hyperlipidemia-associated PIs in HAART regimens improves lipid profiles and maintains virologic suppression over a 28-week period, and it simplifies treatment." (PMID 15647105, 2005). "The proportion of CD4+ T cells decreased in males and hypertensive individuals but increased in current smokers, and individuals with hyperlipidemia (P < 0.05)." (PMID 37461090, 2023). "In this study, we have addressed if hyperlipidemia impacts human pDC activation, cytokine response and capacity to prime CD4+ T cells." (PMID 35625889, 2022). "We also found that gender, CM therapy, CD4+ T-cell count, FPG, and Hb were risk factors for the prevalence of hyperlipidemia in PLWHA (P<0.05)." (PMID 35929632, 2022). "In this study we therefore aimed to investigate the effect of hyperlipidemia on human pDC activation and CD4+ T cell polarization capability in vitro." (PMID 35625889, 2022). "The results of univariate logistic regression analysis showed that gender, CM therapy, CD4+ cell count, FPG, and Hb were risk factors for hyperlipidemia in PLWHA (P<0.05)." (PMID 35929632, 2022). "To characterize hyperlipidemia-induced transcriptomic reprogramming in splenic Tregs of ApoE–/– mice, we performed RNA-Seq on splenic CD4+Foxp3+ Tregs of ApoE–/– mice and WT mice." (PMID 34622804, 2021). "We found that patients with hyperlipidemia (n = 129) showed a higher CD4+ T cell percentage than that of healthy donors (n = 110)." (PMID 33981738, 2021). "We propose that while B cells are not critical for activation and induction of T cells in systemic responses, B cells are critically required for CD4 T cells in specific antigen responses, such as lipid antigen in the setting of persistent hyperlipidemia." (PMID 31998318, 2019). "Multivariate analysis showed that CD4+ cell count 350-500 cells/μL (OR = 1.72, 95% CI: 1.26-2.38), CD4+ cell count >500 cells/μL (OR = 2.49, 95% CI: 1.85-3.38), and FPG >6.2 mmol/L (OR = 2.08, 95% CI:1.64-2.65) were risk factors for hyperlipidemia." (PMID 35929632, 2022). "Female patients, those with baseline CD4+ T-cell count >500 cells/μL, patients with FPG >6.2 mmol/L, and those with Hb ≤110 g/L had 0.72 times, 2.49 times, 2.08 times, and 0.59 times higher risk of developing hyperlipidemia, respectively." (PMID 35929632, 2022). "Female patients with baseline CD4+ T-cell count >500 cells/μL, those with FPG >6.2 mmol/L, and patients with Hb ≤110 g/L had 0.72 times, 2.49 times, 2.08 times, and 0.59 times higher risk of developing hyperlipidemia, respectively." (PMID 35929632, 2022). "Consequently, the impact of hyperlipidemia on CD4+ T cell abnormalities was investigated." (PMID 39266539, 2024). "As patients in this study had mean CD4+ cell counts >500 cells/mm3, they were highly immunocompetent and may not be representative of typical HIV-infected patients presenting to their physician with PI-associated hyperlipidemia." (PMID 15647105, 2005). "After adjusting for other confounding factors in multivariable logistic regression, gender, CD4+ cell count, FPG, and Hb were found to be independent influencing factors of hyperlipidemia (P<0.05)." (PMID 35929632, 2022). "Gender, CD4+ cell count, FPG, and Hb were influencing factors of hyperlipidemia." (PMID 35929632, 2022). "Gender, CD4+ cell count, FPG, and hemoglobin were influencing factors of hyperlipidemia." (PMID 35929632, 2022).
hyperlipidemia (continued). "In hyperlipidaemia pancreatitis, the CD4+T lymphocytes presented an AUC of 0.81, the CD19+ B lymphocytes showed an AUC of 0.79, the combination of CD4+T and CD19+ B lymphocytes had an AUC of 0.83, and the AUC of the APACHE II score and Ranson score were 0.60 and 0.54, respectively." (PMID 30627533, 2018).
Hypoalbuminemia (29 papers, 2006 to 2025). The concentration of albumin in the blood circulation is below the lower limit of normal. "The findings of the present study highlight that hypoalbuminemia is associated with advanced HIV disease, and lower CD4 counts and high viral load counts were observed in patients with hypoalbuminemia." (PMID 40898300, 2025). "At baseline, low hemoglobin, hypoalbuminemia and low CD4 levels were associated with a BMI < 18.5 kg/m2." (PMID 26825478, 2015). "This study seeks to determine the correlation between serum albumin and CD4 cell count, and identify the determinants of hypoalbuminemia in PLWHIV." (PMID 40898300, 2025). "We found that age, extranodal sites, bulky mass, CD4 T-cell counts, CD4/CD8 ratio, and hypoalbuminemia were associated with OS (all P < 0.05) at both univariate and multivariate analyses." (PMID 35873145, 2022). "In that study, 60 percent of HIV-positive patients had hyperproteinemia, and all of them had hypoalbuminemia and hypergammaglobulinemia according to their CD4+ T-cell counts." (PMID 32148675, 2019). "Conducting the urine LAM assay in combination with sputum AFB smear improved diagnostic accuracy, and was most valuable among patients with functional impairment (low Karnofsky Performance score), hypoalbuminemia, or a low CD4 count (<200/mm3)." (PMID 26865526, 2016). "Due to its correlation with CD4, both pre and post ART initiation, and its association with mortality despite HAART, hypoalbuminemia has been proposed as a marker of disease progression and treatment response in LMIC." (PMID 26825478, 2015). "Correlation between hypoalbuminemia and CD4 count among HIV-infected patients." (PMID 40898300, 2025). "Hypoalbuminemia prevalence was high in PLWHIV, and a moderate positive correlation was found between the serum albumin level and the CD4 cell count." (PMID 40898300, 2025). "The laboratory features are characterised by deranged CD4 counts, hyperglobulinaemia,inverted CD4/CD8 ratios and hypoalbuminaemia." (PMID 25940120, 2015). "Previous studies have shown that host factors that are significantly associated with indeterminate QFT results are immunosuppressive therapies, extremes of age, lymphocytopenia, hypoalbuminemia, and HIV-infection with lower CD4 lymphocyte counts." (PMID 21513568, 2011). "Besides, laboratory disparities involved higher CD4 + T-cell counts, lower LDH, and reduced hypoalbuminemia." (PMID 41166393, 2025). "Prognostic factors of mortality for HIV patients admitted to the ICU include CD4 count; APACHE II score; features of organ failure (evidenced by the need for mechanical ventilation, renal replacement therapy, and vasopressor support); and hypoalbuminemia." (PMID 27800179, 2016).
Myelopathy (29 papers, 2006 to 2026). Myelopathy is an descriptive term, referring to pathology leading to a neurologic deficit related to the spinal cord. "Patients with HTLV-1-associated myelopathy display an increased frequency of CD4+CD8+ double positive T cells with an inflammatory phenotype driven by HTLV-1 infection of single positive T cells." (PMID 38193535, 2024). "Further risk stratification of asymptomatic carriers into those at an increased risk of myelopathy is aided by measuring markers of T-cell activation, i.e., cell surface markers on CD4 and CD8 cells." (PMID 37066106, 2023). "Additionally, myelopathy associated with HTLV-1 and cutaneous manifestations in HTLV-1-infected patients have been observed to involve reduced CD4/CD8 ratios in peripheral blood and local infiltration of activated CD8+ cells." (PMID 39691733, 2025). "Moreover, the recovery of CD4+ cells from 4% to 14% after starting antiretroviral treatment might also have contributed to the extension of myelopathy." (PMID 36072168, 2022).
ankylosing spondylitis (28 papers, 2005 to 2026). An autoimmune chronic inflammatory disorder characterized by inflammation in the vertebral joints of the spine and sacroiliac joints. "KIR3DL2-expressing natural killer (NK) cells and IL17 secreting CD4 T cells have been implicated in the pathogenesis of ankylosing spondylitis." (PMID 23162554, 2012). "Among the KIRs, KIR3DL2, an inhibitory receptor expressed on both NK cells and CD4+ T lymphocytes, plays a critical role in the pathogenesis of ankylosing spondylitis." (PMID 40428751, 2025). "In comparison to healthy controls, samples from ankylosing spondylitis cases notably had higher levels of T cells CD4 naive, T cells regulatory, and neutrophils, but lower levels of T cells CD4 memory activated, T cells gamma delta, and NK cells resting." (PMID 39131703, 2024). "KIR‐3DL2+CD4+ T cells in patients with ankylosing spondylitis were oligoclonal and enriched for markers of T cell activation and for the gut homing receptor CCR9." (PMID 26841353, 2016). "In ankylosing spondylitis (AS), as in other immune-mediated diseases, an unusual proinflammatory and cytotoxic CD4+ T-cell subgroup has been described, which lacks the co-stimulatory molecule CD28." (PMID 16277694, 2005). "Increased percentage of CD4+CXCR5+PD-1+ cells has been reported in two studies and was negatively correlated with the Bath Ankylosing Spondylitis Disease Activity Index (BASDAI)." (PMID 36883249, 2023). "At present, when clinical studies are concerned with the relationship between ankylosing spondylitis and regulatory T cells, it is recognized that regulatory T cells mainly include CD4+CD25+, CD4+CD25highFOXP3+, and CD4+CD25highCD127low cells." (PMID 32149142, 2020). "In ankylosing spondylitis, TLR4 (23.1 ± 21.9%) and, to a smaller extent, TLR2 (4.1 ± 5.8%) were expressed on CD4+CD28null T cells, whereas expression was negligible on CD4+CD28+ and CD8+ T cells." (PMID 16277694, 2005). "Furthermore, in ankylosing spondylitis, cumulative evidence indicates ligation of KIR3DL2 on Th17 CD4+ T cells may promote their accumulation and survival." (PMID 39724143, 2024). "Similarly, in ankylosing spondylitis, there was a positive correlation with neutrophil levels and a negative correlation with T cells CD4 naive and T cells CD4 memory resting." (PMID 39131703, 2024).